MYD88 (MYD88 innate immune signal transduction adaptor)
Diseases named in the same sentence as MYD88 in open-access papers (continued):
Sharing a sentence is not in itself a finding about the gene and the disease.
hepatic granuloma (2 papers, 2010 to 2014). A granuloma located in the liver. "As expected, MyD88, which is a key signal adapter molecule of the major TLR signal pathway, is essentially required for the development of hepatic granulomas after P. acnes priming, strongly suggesting critical role of TLR/MyD88 pathway in the development of P. acnes-induced LPS sensitization." (PMID 20634907, 2010). "Therefore, it is plausible that Myd88−/− mice do not develop hepatic granulomas after P. acnes treatment." (PMID 24802875, 2014).
hepatitis C (2 papers, 2016 to 2023). "In addition, miR-21 is upregulated during hepatitis C virus infection and negatively regulates IFN-α signaling through MyD88 and IRAK1; it may thus be a potential therapeutic target for antiviral intervention." (PMID 27213347, 2016).
hyper-IgE syndrome (2 papers, 2019 to 2024). A condition that is characterized by elevated serum IgE, dermatitis, and respiratory infections. "In the second Ion Torrent negative patient (PID82) presenting an atypical HyperIgE syndrome, Haloplex detected two rare homozygous mutations in MYD88 and CARD9 genes, which were not included in the Ion Torrent panels (1 and 2)." (PMID 31031743, 2019).
immunotoxicity (2 papers, 2019 to 2023). "Previous studies have shown that OTA mediated immunotoxicity of the TLR4/MyD88 signaling pathway by inducing an increase in reactive oxygen species in porcine alveolar macrophages." (PMID 31533259, 2019).
intestinal infection (2 papers, 2017 to 2021). "To further elucidate the mechanism by which IEC-restricted MyD88 signaling contributes to enhanced protection from intestinal infection, we analyzed the IEC-specific expression of factors involved in host resistance to Citrobacter." (PMID 28520792, 2017). "MyD88-dependent signaling pathways play a critical role in the protective immune response during intestinal infections." (PMID 28520792, 2017). "In order to investigate the consequences of IEC-specific MyD88 activation on the host defense upon intestinal infection, we generated IEC-MyDON mice by crossing MyDOFF mice with mice expressing Cre under the promotor of Villin, thus allowing the efficient expression of MyD88 in IEC." (PMID 28520792, 2017). "In order to investigate the influence of MyD88 signaling specifically in T cells and ILC3 during intestinal infection, we generated Rorc-MyDON mice by crossing MyDOFF mice with mice expressing Cre under the promotor of Rorc(γt)." (PMID 28520792, 2017). "Together, our data suggest that MyD88 signaling in DC and IEC is both essential and sufficient to induce a full spectrum of host responses upon intestinal infection with C. rodentium." (PMID 28520792, 2017). "In order to investigate the importance of MyD88 in specific immune and nonimmune cell types during intestinal infection, we employed a novel murine knock-in model for MyD88 that enables the cell type-specific reactivation of functional MyD88 expression in otherwise MyD88-deficient mice." (PMID 28520792, 2017). "However, ILC3 from MyD88-deficient animals failed to upregulate the production of IL-22 and IL-17 upon intestinal infection, suggesting that MyD88-mediated signaling is strictly required for the functional activation of ILC3 after pathogenic challenge." (PMID 28520792, 2017). "Moreover, MyD88 signaling in both hematopoietic as well as non-hematopoietic cells and tissues has been suggested to contribute to host defense and mucosal tissue protection following intestinal infection and inflammation." (PMID 28520792, 2017).
intestinal polyp (2 papers, 2014 to 2021). Discrete abnormal tissue masses that protrude into the lumen of the intestine. "A correlation between the TLR/MyD88 signaling pathway and APC mutations was recently proposed since MyD88 signaling was found to facilitate the growth of intestinal polyps while the ablation of MyD88 restricted polyp growth in Apcmin/+/Myd88−/− mice, but not in Apcmin/+ mice." (PMID 25076949, 2014). "MyD88 is important in facilitating the growth of intestinal polyps in Apcmin/+ mice; the roles of TLR/MyD88 signaling pathway in CRC pathogenesis mainly focus on inflammation." (PMID 34385421, 2021).
Legionella infection (2 papers, 2016 to 2025). "Addition of the MTOR inhibitors PP242 or rapamycin to synchronized Legionella infections of Myd88-/- BMMs reduced phosphorylation of S6K1 and its substrate rS6p." (PMID 27942021, 2016). "Given that IL-12 and TNF-α are important cytokines produced upon MyD88 signaling and critical for immunity, we then investigated whether these cytokines are required for the protection induced by an initial Legionella infection." (PMID 40558085, 2025). "Thus, the role of the TLR adaptor Myd88, which is required for LPS-induced MTOR signaling, was investigated in the context of Legionella infection." (PMID 27942021, 2016).
leptospirosis (2 papers, 2014 to 2022). A contagious bacterial infection caused by spirochetes of the genus Leptospira. "We previously showed that Myd88 ko mice are very sensitive to, and die from, acute leptospirosis because of a lack of TLR4 recognition." (PMID 25474719, 2014).
lipid metabolism disorders (2 papers, 2020 to 2026). "Furthermore, we discovered that fgl2 combined with TLR4 mediates the activation of the Myd88-dependent signaling pathway, which may contribute to inflammation and lipid metabolism disorders." (PMID 32863955, 2020).
Listeria infection (2 papers, 2011). "Our findings suggest that Listeria infection in BMDMs regulates both miR-125a-3p/5p and miR-146a at transcriptional levels, the first in a vacuolar/MyD88-dependent manner and the latter in a MyD88-independent manner." (PMID 22114673, 2011). "Because MyD88 signaling cooperates with IFN-I in Ly6Chi monocyte recruitment in a Listeria monocytogenes infection model, we tested whether Toll-like receptor (TLR) or RIG-I-like receptor (RLR) signaling is involved in Ly6Chi monocyte regulation in our model." (PMID 21383977, 2011).
liver cirrhosis (2 papers, 2023). "Conversely, rats received low-dose or high-dose treatment of vitamin D exhibited decreased expression levels of TLR4, MyD88, and phospho-NF-κB p65 (p-NF-κB) in the ileum tissues compared with the liver cirrhosis model group." (PMID 37273916, 2023). "The univariate and multivariate analyses indicated the diagnostic value of various clinical factors (including lnc-MyD88 and AFP) in HBV-related HCC group, and the HBV-related liver cirrhosis group is the control." (PMID 36793272, 2023). "Given the role of TLR4 activation and the downstream adapter MyD88 in activating the NF-κB signaling pathway, we investigated the influences of liver cirrhosis on TLR4/MyD88/NF-κB signaling in ileum tissues using RT-PCR and Western blot analysis." (PMID 37273916, 2023). "In this study, we found the activation of TLR4/MyD88/NF-κB pathway in intestinal tissues of liver cirrhosis rats while the treatment of vitamin D remarkably suppressed the TLR4/MyD88/NF-κB pathway." (PMID 37273916, 2023). "The results showed that liver cirrhosis activated TLR4/MyD88/NF-κB signaling in ileum samples of rats compared with the control group." (PMID 37273916, 2023). "Mechanistically, vitamin D might promote the process of liver cirrhosis-induced intestinal damage repair by suppressing the TLR4/MyD88/NF-κB signaling pathway." (PMID 37273916, 2023). "Quantitative real-time PCR was adopted to detect lnc-MyD88 expression in plasma samples of 98 HCC patients, 52 liver cirrhosis (LC) patients, and 105 healthy people." (PMID 36793272, 2023). "In this study, we revealed that vitamin D suppressed liver cirrhosis-induced intestinal inflammation and oxidative stress through the TLR4/MyD88/NF-κB pathway." (PMID 37273916, 2023). "Moreover, vitamin D effectively inhibited liver cirrhosis-induced intestinal inflammation and oxidative stress through the TLR4/MyD88/NF-κB pathway." (PMID 37273916, 2023).
meningoencephalitis (2 papers, 2021 to 2024). Inflammation of the meninges and brain, generally secondary to an infectious cause. "In addition, E. coli can cause meningoencephalitis by increasing the inflammatory response and activating the TLR2/TLR4/MyD88 and the NLRP3 inflammasome pathways." (PMID 35145923, 2021). "The study evaluates the critical role of Cav-1 regulation through the TLR4/MyD88 signaling pathway, modulates tight junction proteins, influences BBB permeability, and contributes to brain damage in A. cantonensis-induced meningoencephalitis." (PMID 38922036, 2024).
metastasis (2 papers, 2010 to 2012). The spread or migration of cancer cells from one part of the body (where they first appeared) to another. "In addition, CRC with liver metastasis showed higher levels of TLR4 and MyD88 expression than did CRC without liver metastasis (P=0.0015, P=0.0035, P=0.0001, respectively)." (PMID 20145615, 2010).
myositis (2 papers, 2020 to 2023). "Previous work has also shown the importance of coordinated MyD88 signaling in multiple cell types, as global MyD88 knockout mice yield an even more dramatic reduction in myositis than conditional knockout mice following HRS immunization." (PMID 37809058, 2023). "Although antigen-specific T cell proliferation and production of class-switched autoantibodies suggest a role for adaptive immunity in this model, the development of myositis is absolutely dependent on MyD88, with substantial (but overlapping) contributions from TLR2 and TLR4 signaling." (PMID 37809058, 2023). "To define the requirement for myeloid cells such as macrophages and further assess their interaction with T cells in HRS-induced myositis, we generated myeloid-specific MyD88 conditional knockout mice in which Cre recombinase is expressed under the Lyz2 promoter (Lyz2-Cre.MyD88fl/fl mice)." (PMID 37809058, 2023). "The murine models of myositis have demonstrated the importance of TLR2 and TLR4 in the induction of disease in IIM, since the deficiency of both TLRs or their signaling protein MyD88 completely abolish the disease phenotype." (PMID 32164729, 2020). "Overall, HRS-induced myositis reflects the complex interplay between multiple cell types that collectively drive a TH1-predominant, pro-inflammatory tissue phenotype requiring antigen-mediated activation of both MyD88- and TCR-dependent T cell signaling pathways." (PMID 37809058, 2023).
necrotizing enterocolitis (2 papers, 2017 to 2021). Necrotizing enterocolitis (NEC) is a devastating disease that affects mostly the intestine of premature infants. "MYD88 expression was upregulated in patients presented with necrotizing enterocolitis (p = 0.043), transient tachypnea (p = 0.043), poor feeding (p = 0.037), congenital pneumonia (p = 0.021), acquired pneumonia (p = 0.003), and jejunal atresia (p = 0.029)." (PMID 34183713, 2021). "In a UV model of apoptosis, MyD88 signalling appears to reduce caspase-3 and in turn increase cell survival, and more recently B. bifidum has been shown to reduce apoptosis in vitro (necrotizing enterocolitis IEC-6 cell model), as also indicated by reduced CC3-positive cells." (PMID 28123052, 2017).
neuropathic pain (2 papers, 2018 to 2025). Chronic pain caused by damage to nerve fibers. "Consistently, upregulation of TLR4 during the development of DNP in the spinal cord has been identified, and several drugs including coenzyme Q10 and duloxetine contribute to TLR4/Myd88/NF-κB signaling pathway inhibition in the occurrence of neuropathic pain." (PMID 30647535, 2018).
oral cancer (2 papers, 2020 to 2021). "Periodontal pathogens promote the highly aggressive phenotype of oral cancer through crosstalk between integrin/FAK and TLR/MyD88 signaling." (PMID 33799345, 2021). "Taken together, T. denticola promotes OSCC carcinogenesis properties, such as migration, via crosstalk between TLR/MyD88 and integrin/FAK signaling pathways, and thereby contributes to a more aggressive oral cancer phenotype." (PMID 33002094, 2020).
osteoporosis (2 papers, 2024). A condition of reduced bone mass, with decreased cortical thickness and a decrease in the number and size of the trabeculae of cancellous bone (but normal chemical composition), resulting in increased fracture incidence. "miR-1906 mimic reduced bone loss of osteoporosis animal model by down-regulating the TLR4/MyD88/NF-kB pathway." (PMID 38504994, 2024). "It was reported that inhibiting TLR4/MyD88 signaling in osteoclast precursors effectively mitigates the progression of osteoporosis and subsequently bone loss." (PMID 38504994, 2024). "Ultimately, we determined that AR495 and the fermentation broth group can balance bone metabolism by inhibiting the RANK/RANKL/OPG system, as well as the RANKL/TRAF-6 and TLR4/MYD88 pathways, thereby alleviating osteoporosis." (PMID 39410150, 2024). "AEG-1 deletion improved bone remodeling in an osteoporosis animal model by inhibiting TLR4/MyD88/NF-κB pathway." (PMID 38504994, 2024).
otitis media (2 papers, 2014). Inflammation of the anatomical structures of the middle ear, which is most often caused by an infectious process. "In addition to our prior study showing that lysozyme deficiency inhibits pneumococcal clearance from the middle ear cavity, MyD88 deficiency is known to delay resolution of NTHi-induced otitis media." (PMID 24625812, 2014). "Previous candidate gene studies associated a number of immune system genes with otitis media, which included TNF-α, IL-6, IL-10, Tlr4, surfactant, CD14, FcγRIIa, IFNγ, Eya4, p73, MyD88, Fas, E2f4, Plg, Fbxo11, and Evi1." (PMID 24466073, 2014).
paracoccidioidomycosis (2 papers, 2014 to 2019). A systemic fungal infection caused by Paracoccidioides brasiliensis that is most often seen in immunocompromised patients. "Our previous studies in murine paracoccidioidomycosis have shown that the expansion of IL-17 producing cells is controlled by several pathogen recognition receptors (TLR-2, TLR-4, dectin-1) as well as the IL-1R and Toll adaptor protein, MyD88." (PMID 25411790, 2014).
peripheral nerve injury (2 papers, 2017 to 2018). Injury to a peripheral nerve. "Our recent studies show that suppression of myeloid differentiation factor-88 adaptor protein (MyD88)-dependent signaling alleviates neuropathic pain induced by peripheral nerve injury in the rat." (PMID 29885668, 2018). "Our recent study demonstrated that MyD88-dependent signaling pathway of TIR in the dorsal root ganglion (DRG) and spinal dorsal horn (SDH) plays a role in peripheral nerve injury-induced neuropathic pain." (PMID 29885668, 2018). "Recent publications show that MyD88, adaptor protein of TLRs and IL-1R, is also found in the expression in DRG and spinal cord.We hypothesized that suppressed MyD88 adaptor protein in the DRG and spinal cord could alleviate peripheral nerve injury-induced neuropathic pain." (PMID 28359290, 2017).
Pleuritis (2 papers, 2008 to 2015). Inflammation of the pleura. "In contrast, Myd88-/- mice demonstrated strongly reduced lung inflammation early after infection with D39 (P<0.01 vs WT mice), caused by reduced pleuritis, interstitial inflammation, bronchitis, endothelialtis and edema." (PMID 25700108, 2015). "Pulmonary inflammation was characterized by significant inflammation, pleuritis, peribronchial inflammation, oedema and endothelialitis in both WT and MyD88 KO mice." (PMID 18946505, 2008).
pneumococcal pneumonia (2 papers, 2012 to 2015). A febrile disease caused by STREPTOCOCCUS PNEUMONIAE. "Previous studies have implicated TLR9 and MyD88 as important players in protective immunity in pneumococcal pneumonia." (PMID 22721450, 2012). "In accordance with a role for TLR signaling in host defense against pneumococcal pneumonia, MyD88 deficient (Myd88-/-) mice were reported to show a profoundly enhanced growth of pneumococci and a strongly reduced survival after intranasal infection with serotype 4 or 19F S. pneumoniae strains." (PMID 25700108, 2015).
prostate carcinoma (2 papers, 2014 to 2018). A carcinoma that arises from epithelial cells of the prostate gland. "Loss of the critical downstream TLR signaling component MyD88 significantly worsens the phenotypes in mouse models of prostate cancer, but these effects appear to be indirect and reflect the role of MyD88 in immune cells." (PMID 30158439, 2018). "We showed that prostate cancer cell lines differentially express TLR1-10, MyD88 and CD14 transcripts." (PMID 24966802, 2014). "Expression of TLR1-10, MyD88 and CD14 in prostate cancer cells, LNCaP, PC3 and DU145, was studied by RT-PCR." (PMID 24966802, 2014). "Therefore we examined and compared expression of TLR1-10, MyD88 and CD14 and functional responsiveness to TLR-2 and 4 ligands in well-established prostate cancer cell lines." (PMID 24966802, 2014).
Pseudomonas infection (2 papers, 2017 to 2024). Infections with bacteria of the genus pseudomonas. "PumA ensures efficient inhibition of innate immune responses by interacting with MyD88 and TIRAP, key adaptor proteins for IL‐1R and the main relevant TLRs in Pseudomonas infection (TLR4 and TLR5), as well as UBAP1 which regulates cytokine receptor pathways." (PMID 28483816, 2017).
pulmonary hypertension (2 papers, 2022). Increased pressure within the pulmonary circulation due to lung or heart disorder. "Pharmacological experiments also showed that geniposide can protect pulmonary artery smooth muscle from lipopolysaccharide damage by affecting the tlr-4/myd88 signalling pathway, improve pulmonary function, and avoid the formation of pulmonary hypertension." (PMID 35356238, 2022).
pulpitis (2 papers, 2021 to 2025). Inflammation of the dental pulp. "Thus, the TLR4/MyD88-mediated NF-κB and p38 MAP kinase pathways are considered to be crucial signaling axes in LPS-induced pulpitis." (PMID 34785637, 2021).
Q fever (2 papers, 2019 to 2023). A bacterial infection caused by Coxiella burnetii. "Our findings are consistent with previous studies using TLR2- and MyD88-deficient mice and with the association of a polymorphism in human Myd88 with the development of chronic Q fever." (PMID 30800124, 2019). "Here, we identify the ACOD1‐ITA axis as a key MyD88‐dependent macrophage‐autonomous determinant of early containment of C. burnetii and control of Q fever." (PMID 36479617, 2023). "Infection of Myd88−/− mice with the attenuated NMII strain proved to model important aspects of chronic Q fever (prolonged C. burnetii load in several tissues; impaired granuloma formation; and altered cytokine expression)." (PMID 30800124, 2019). "The robust differences in bacterial loads observed here in Myd88−/− mice, indicate that infection with NMII can be successfully employed to model chronicity of Q fever." (PMID 30800124, 2019).
respiratory infection (2 papers, 2014 to 2016). "Although MyD88 is an adapter molecule for all three of these TLRs, mice deficient in Myd88 show a similar phenotype to deficiency in Tlr5 after respiratory infection with B. pseudomallei." (PMID 25232720, 2014). "These genes are directly involved in innate immune sensing (TLR, MYD88, JAK/STAT), and inflammation (IL-6, IFN, TNF, IL-10, IL-22) which are two common host signaling pathways activated by bacteria and viruses during acute respiratory infections." (PMID 27532264, 2016).
retinal (2 papers, 2014 to 2025). "However, the role of two Tlr4-dependent signaling cascades, myeloid differentiation primary response 88 (Myd88) and TIR-domain-containing adapter inducing interferon-β (Trif), in retinal IR injury is poorly understood." (PMID 24754835, 2014).